CD14 (CD14 molecule)
Diseases named in the same sentence as CD14 in open-access papers (continued):
Sharing a sentence is not in itself a finding about the gene and the disease.
COVID-19 (continued). "In HSPCs of COVID-19, late-phase CD14+ monocytes retain elevated levels of inflammatory mediators such as S100A8 and S100A9 relative to both healthy controls and early-phase samples, underscoring their progression toward a more differentiated, pro-inflammatory phenotype." (PMID 41550933, 2025). "Studies indicate that pregnant women with COVID-19, particularly in their third trimester, experience a dysregulation of innate immunity, characterized by lower levels of IFNγ and reduced expression of CD14 and HLA-DR on monocytes." (PMID 40497938, 2025). "Presepsin, a cleaved peptide of soluble CD14, may become a promising biomarker for assessing disease severity and mortality in coronavirus disease 2019 (COVID-19)." (PMID 40143286, 2025). "Notably, a CD14+ CD3+ double-positive subset was described in a study with convalescent COVID-19 patients before, which aligns with our observation." (PMID 38391913, 2024). "Importantly, our finding is consistent with another previous report of circulating CD14+ CD3+ double-positive cells in convalescent COVID-19 patients." (PMID 38391913, 2024). "In particular, CCL3, IL1RN, and TNF-high CD14 monocytes are enriched in patients with severe COVID-19 and may accompany inflammatory storms." (PMID 39712003, 2024). "Notably, these genes characterize a CD14+ immunosuppressive monocytic myeloid-derived suppressor cell population MS1 recently described in bacterial sepsis and COVID-19 as negatively associated with survival." (PMID 38890515, 2024). "We assessed this importance score for CD14+ monocytes in small COVID-19 datasets." (PMID 39218971, 2024). "Moreover, scRNA-seq of peripheral blood monocyte cells (PBMCs) from COVID-19 patients revealed a significant increase in the proportion of CD14+ monocytes, in which 38 of 59 hub genes were highly enriched." (PMID 36817436, 2023). "We identified the cellular source for pro-inflammatory cytokine storm in COVID-19 acute necrotizing encephalopathy patients as primarily originating from three cell subtypes, a CD14+ monocyte subset (Mono_CD14), a proliferative CD8 T subset (CD8_Pro) and a CD4 memory T subset (CD4_Memory)." (PMID 37848421, 2023). "Indeed, we found that this signature was even stronger in CD14+ cells of healthy donors post-vaccination than in vaccinated patients who had recovered from COVID-19." (PMID 37369668, 2023). "Furthermore, SARS-CoV-2 spike protein was expressed in CD14+ monocytes in PBMCs isolated from patients who had recovered from COVID-19, consistent with recent findings." (PMID 37369668, 2023). "In line with this hypothesis, MIS-C children had increased LPS-binding protein and CD14 plasma levels, which are both markers of microbial translocation, compared to children with acute uncomplicated COVID-19 and pre-pandemic control children." (PMID 37006315, 2023). "Similarly, SPDEF and ELF3 were found to be activated in squamous cells, and CEBPD and FOS were shared between CD14 and CD14 monocytes in severe COVID-19." (PMID 37936693, 2023). "Severe COVID-19 cases exhibit aberrant immune responses, compromised innate-adaptive crosstalk, and alterations in peripheral blood cell composition, including elevated CD14+ and CD16+ monocytes and reduced overall B cells." (PMID 38022594, 2023). "Likewise, we found that compared to the number of upregulated genes, a larger number of genes tended to be downregulated in most cell types from PBMCs, and the highest differences between healthy and severe COVID-19 patients were noted in CD14 monocyte cells." (PMID 37936693, 2023). "The mechanism of the increase in IL-6 in COVID-19 patients may be the release of IL-6 from respiratory epithelial cells, CD14 + CD16 + monocyte-macrophages and lymphocytes after infection." (PMID 37310657, 2023). "The highest expression of PKM in COVID-19 ARDS patients is found in circulating mono-CD14+ cells." (PMID 36776845, 2023).
COVID-19 (continued). "However, both pregnant and nonpregnant women had an increase in HLA-DR+CD38+ CD8+ T cells and CD14+ classical monocytes during acute COVID-19, as compared with their respective healthy group." (PMID 37036008, 2023). "Among the DEGs in CD14+ monocytes, 1265, 899, 332 and 232 genes were upregulated in COVID-19 patients with mild-moderate disease, severe disease, acute necrotizing encephalopathy and non-acute necrotizing encephalopathy, respectively, of which, 175 were shared." (PMID 37848421, 2023). "Previous research has shown downregulation in proteins related to neutrophil degranulation in milk in response to COVID-19, but CD14 downregulation would also mean that there are fewer MNPs in the colostrum of COVID-19 patients, perhaps as a result of recruiting to COVID-19-infected tissues." (PMID 37628421, 2023). "Moreover, a significant upregulation of TF in circulating CD14+ monocytes and BAL cells such as macrophages was observed in COVID-19 patients, indicating a critical role of the TF-triggered extrinsic pathway in COVID-19-associated systemic thrombosis." (PMID 38069229, 2023). "In PPASC, we observed interactive VEGF ligand-receptor pairs among MLCs, and network modules in CD14+ (cluster 4) and CD16+ (Cluster 5) monocytes displayed a significant enrichment for biological pathways linked to adverse COVID-19 outcomes, fibrosis, and angiogenesis." (PMID 38259488, 2023). "Moreover, a substantial increase in the proportion of blood inflammatory monocytes (CD14+CD16+ cells) capable of secreting IL-6 has been reported in COVID-19 patients with severe disease." (PMID 35284964, 2022). "Immunofluorescence analysis revealed an increased expression of c-FLIP in circulating CD14+ cells isolated from COVID-19 patients compared to heathy donors (HDs), together with a linear correlation between c-FLIP-expression in monocytes and their immunosuppressive properties." (PMID 34518653, 2022). "Our transcriptomic and epigenomic analysis of CD14+ monocytes indicated that the functional alterations identified in patients with acute severe COVID-19 are accompanied by decreased basal activity of key modules involved in TLR signaling pathways, including NF-κB and AP1." (PMID 35380990, 2022). "In this report, we demonstrate that COVID-19 plasma exosomes stimulate protein expression of TLR3 as well as TLR7 and TLR9 in CD4+ T cells, CD8+ T cells, and CD14+ monocytes compared with cells that remained untreated, treated with plasma exosomes from non-COVID-19 or healthy donors, or poly(I:C)." (PMID 36526691, 2022). "Taken together, our results suggest PIRAT and LUCAT1 to regulate largely discrete sets of genes in CD14+ monocytes during COVID-19, with LUCAT1 inhibiting STAT and promoting NF-κB target gene expression and PIRAT serving as a withdrawable inhibitor of PU.1-dependent programs." (PMID 35998224, 2022). "Furthermore, CD14+CD16+ monocytes were detected at high frequency in COVID-19 respiratory samples than in blood samples." (PMID 35898494, 2022). "Indeed, compared with acute pediatric COVID-19, biomarkers indicating increased intestinal permeability (zonulin, LPS-binding protein, and soluble CD14) are elevated in the plasma of MIS-C patients." (PMID 35874696, 2022). "In summary, we found that the evolution of the chromatin landscape in circulating leukocytes during COVID-19 primes host immunological responses at early times, is mediated primarily by CD14+ monocytes and correlates with an observed divergence in disease severity." (PMID 35810186, 2022). "Altogether, our transcriptomic data on CD14+ monocytes from patients with acute severe COVID-19 indicate that these cells display an altered profile that could account for their decreased responsiveness to PAMPs." (PMID 35380990, 2022).
COVID-19 (continued). "In contrast to the peripheral lymphopenia that is associated with acute COVID-19, we found that in this post-COVID-19 patient cohort the frequency of T cells, B cells, and CD14+ monocytes in the peripheral blood was similar to HCs, although the proportion of NK and NKT cells was decreased." (PMID 35151371, 2022). "Moreover, CD14 + CD16 + CD206 + CD163 + CD123 + interstitial macrophages were increased in lungs with late COVID-19 compared to healthy lungs." (PMID 35698166, 2022). "We identified a significant direct correlation between pSTAT3 and c-FLIP expression in circulating CD14+ cells isolated from COVID-19 patients, hinting to the aberrant activation of FLIP/STAT3 axis in myeloid cells not only at pulmonary site but also in periphery." (PMID 34518653, 2022). "Xu and co-authors hypothesized that monocytes in severe COVID-19 displayed a phenotype similar to immunosuppressive monocytic myeloid-derived suppressor cells (CD14+/HLA-DR-/lo)." (PMID 35213582, 2022). "To gain further insight into the molecular features of CD14+ monocytes in these severely affected patients with COVID-19 during acute and convalescent stages, we selected only hospitalized patients from our cohort and age- and sex-matched controls, and we performed global transcriptional profiling." (PMID 35380990, 2022). "Additionally, the classical CD14++CD16- monocytes of severe COVID-19 patients showed inflammasome activation, as evidenced by caspase-1/ASC-speck activation." (PMID 35757770, 2022). "Thus, CD14+ monocytes from both mild and moderate COVID-19 patients were able to efficiently activate SARS-CoV-2-specific CD8+ T cells upon UV-inactivated SARS-CoV-2 stimulation." (PMID 36572683, 2022). "Representative dot-plots exemplify the contrast of CD14++CD16+ intermediate monocytes expressing IFN-alpha in whole blood samples exposed to polyclonal molecules from participants who experienced mild or severe COVID-19 throughout the follow-up." (PMID 35860236, 2022). "RNA sequencing of the early recovery stage of COVID-19 showed that classical CD14++ and CD14++ IL-1β+;monocytes are of greater abundance with high expression of inflammatory genes, indicating that IL-1β may be a potential target for the COVID-19 intervention." (PMID 36090995, 2022). "Mon HLA and Mon CD14 inside Delta samples differ in expression for the cytokine panel (CCL3, VEGFA, CCL5, CCL4, CXCR4, IL7R, CXCL8, and PF4) that have been found associated with COVID-19 severity and mortality." (PMID 36230912, 2022). "Changes in the expression levels of TNFSF10 and IFITM2 in CD14+/CD16+ monocytes may affect the immune response of COVID-19 patients." (PMID 36555339, 2022). "In patients with non-COVID-19 viral infections, we observed significant increase in proportion for myeloid cells (M1 macrophages, CD14 + monocytes, MAST cells) and significant decrease in proportion for lymphoid cells (CD4+ and CD8+ T cells, gamma-delta T cells, B cells)." (PMID 33437935, 2021). "Additionally, mono-CD14+ cells in mildly ill COVID-19 patients showed enhanced glycolysis, which promoted their proinflammatory functions and IFN-mediated antiviral response." (PMID 33936072, 2021). "Specifically, three coexpression modules in COVID-19 patients were identified in mono-CD14+ cells." (PMID 33936072, 2021). "The massive increase in mono-CD14+ cells in patients with severe COVID-19 could incite cytokine storm along with an impaired IFN response." (PMID 33936072, 2021). "A higher frequency of CD163+ CD14+ cells in the DC3 subpopulation correlated with systemic inflammation suggesting that these cells may play a role in inflammatory responses of COVID-19 patients." (PMID 34614036, 2021). "These genes may contribute to the hyperinflammation in mono-CD14+ cells of patients with severe COVID-19." (PMID 33936072, 2021).
COVID-19 (continued). "In the peripheral blood of COVID-19 patients, where the total number of monocytes and macrophages was similar to healthy individuals, a high forward scatter monocyte population double-positive for CD14 and CD16 has been identified." (PMID 34209845, 2021). "We, therefore, hypothesized that the CD163+ CD14+ fraction within DC3 is also expanded in COVID-19 patients." (PMID 34614036, 2021). "This notion is supported by recent evidence, suggesting that SARS-CoV-2 infections are associated with profound alterations in the myeloid compartment, with dysfunctional HLA-DRloCD163hi and HLA-DRloS100Ahi CD14+ monocytes prevailing in a severity-dependent manner in COVID-19." (PMID 33126054, 2021). "SETDB2 protein was also decreased in CD14+ monocytes from COVID-19 (+) patients." (PMID 34479991, 2021). "Therefore, attempting a comparison between alloHSCT patients and those with COVID-19, evaluation of CD14+HLADR- cells in both these situations was of great importance." (PMID 34149697, 2021). "We cannot expand the study population for further research, and we suggest dynamic monitor of CD14+HLA-DRlo/neg MDSCs in COVID-19 patients could help to evaluate its detailed clinical values and roles in development of COVID-19 in current outbreak areas." (PMID 33640878, 2021). "Particularly, the relative abundance of naïve T cells, mucosal-associated invariant T (MAIT) cells and monocyte-derived DCs decreased with the severity of COVID-19, whereas the proportions of proliferative T cells, plasma B cells, CD14+ monocytes and platelets increased with the disease severity." (PMID 33912590, 2021). "However, CD14+ monocytes were significantly reduced two weeks after infection in the severely affected COVID-19 patients." (PMID 34867933, 2021). "The percentage of CD14+ cells decreased in the blood of COVID-19 patients compared to the control." (PMID 34960790, 2021). "Moreover, as previously observed for the mDCs, also COVID-19 patients CD14+ monocytes showed an impaired ability to answer to TLR stimulation, reinforcing the idea of an impaired innate response during COVID-19 disease." (PMID 34595175, 2021). "The frequencies of CD14+CD16+ Monocyte observed in COVID-19 patients and controls (NP, NN, and NA) revealed a slight quantitative decrease in the PP group, which was not correlated with age, conversely, a quantitative increase in NP correlated with age was observed." (PMID 34683357, 2021). "Interestingly, dysfunctional HLA-DRhigh and HLA-DRlow CD14+ monocytes in severe COVID-19 were already characterized using an integrated approach involving mass cytometry (CyTOF), scRNA-Seq and flow cytometry assays." (PMID 34944610, 2021). "Among the differentially expressed genes (DEGs) in CD14+ monocytes, we found 116 and 134 upregulated genes in mild COVID-19 and severe COVID-19 cases compared to controls, vs only 74 upregulated genes in comparison between the two COVID-19 groups." (PMID 33101705, 2020). "Thus those upregulated DEGs in CD14+ monocytes from COVID-19 patients reflect the immune response to SARS-CoV-2 infection, while the downregulated DEGs in CD14+ monocytes from patients with severe COVID-19 suggest an immune paralyzed status of those cells." (PMID 33101705, 2020). "COVID-19 early recovery stage was characterized by CD14 ++ monocytes with high inflammatory gene expression as well as by the abundance of CD14 ++IL1β + cells, while T cells decreased remarkably, compared with both late recovery stage and healthy control subjects." (PMID 33129318, 2020). "Similarly, a greater proportion of CD14++ CD16− IL1β+ monocytes were detected in COVID-19 patients by RNA sequencing, which found expression in CD14++ monocytes of pro and anti-inflammatory genes were up and down-regulated, respectively when compared to HCs." (PMID 33123152, 2020).
COVID-19 (continued). "Furthermore, we found that the proportion of CD14+ monocytes is positively correlated with the suppression of HLA_DR+ Tregs, and the proportion of CD14+ monocytes in severe COVID-19 patients is higher than in other COVID-19 patients." (PMID 40114921, 2025). "Therefore, the ligand-receptor pair of PF4_CXCR3 from the interaction between CD14+ monocytes and HLA_DR+ Tregs may contribute to the activation of HLA_DR+ Tregs in COVID-19 patients." (PMID 40114921, 2025). "To experimentally validate whether NK cell–monocyte interactions could indeed underlie NK cell activation in severe COVID-19, we developed an allogeneic coculture system in which CD14+ monocytes from COVID-19 patients were isolated and cocultured with NK cells derived from healthy donors." (PMID 38578283, 2024). "Therefore, our data indicated that genes such as Il1b, S100a, Il1rn and other inflammatory factors which were highly expressed by CD14+ monocytes, may be the main contributors to the cytokine storm in COVID-19." (PMID 36817436, 2023). "Interestingly, CD14-expressing monocytes (Mono_CD14), which were the largest contributors of inflammatory cytokine storm in COVID-19 acute necrotizing encephalopathy patients, have been validated as critical sources of cytokine storms in patients with severe COVID-19 disease in a previous study." (PMID 37848421, 2023). "Interestingly, the presence of CD14, which is an innate immunity marker produced by macrophages and neutrophils was similar in both healthy control subjects and Long-COVID patients, but significantly depleted in mild and severe COVID-19 patients." (PMID 37301958, 2023). "There was a significantly higher percentage of CD14+CD16+ monocytes in peripheral blood from severe COVID-19 patients than in blood from mild COVID-19 patients, suggesting that pro-inflammatory monocytes might be strongly involved in the pathogenesis of the infection." (PMID 36558818, 2022). "Finally, ∼10% of the COVID-19 specific signature genes were preferentially expressed in CD14 monocytes and ∼1% in CD16 monocytes, including both upregulated and downregulated genes; many of these genes were also expressed in neutrophils in the whole-blood Combes data." (PMID 35991542, 2022). "Recently described CD56+CD14+Ki67+IFN-γ+ monocyte may play a crucial role in severe COVID-19." (PMID 35466278, 2022). "However, the COVID-19-related protein RPL19 was negatively correlated with CD14 and B cells naive." (PMID 35720320, 2022). "Indeed, large studies on the general population showed that patients in severe-stages of COVID-19 had increased amounts of circulating CD14+ CD16+ monocytes which exert inflammatory activity through increased release of IL-6 and interaction with adaptive B and T-cells." (PMID 35267478, 2022). "Also, monocytes from COVID-19 patients with severe disease downregulate HLA class II encoding genes and CD4 expression, which is associated with monocytes-to-macrophage differentiation and proinflammatory CD14 monocyte sub-population." (PMID 35284964, 2022). "As the known CXCR3 ligands, CXCL9, CXCL10, and CXCL11, are predominantly induced by IFNγ, the presence of this CXCR3-expressing CD11b+CD14+ monocyte subset may be mechanistically related to the synchronous increase in the IFNγ-producing CD4+ T cell subset in our convalescent COVID-19 cohort." (PMID 34113347, 2021). "The frequency of CD14+HLA-DRlo/neg MDSCs could be used as a predictor of COVID-19 severity." (PMID 33640878, 2021). "Additionally, we provide a number of early prognostic markers for the onset of severe COVID-19, such as CD14+/CD16+ monocytes ratio, CD4+/CD8+T cell ratio, GZMK+/GZMB+ T cell ratio, etc., although these parameters require further validation in the larger cohorts." (PMID 35095917, 2021).